MYC (MYC proto-oncogene, bHLH transcription factor)
Diseases named in the same sentence as MYC in open-access papers (continued):
Sharing a sentence is not in itself a finding about the gene and the disease.
ovarian carcinoma (continued). "Increased MYC expression potentially contributes to the increased metabolic phenotype of ovarian cancers through increased glycolysis mediated by lactate dehydrogenase as well as glutamine addiction in MYC-driven cancers." (PMID 34031395, 2021). "High c-MYC, low p27, and high phosphorylated Rb protein signature correlates with poor patient survival in ovarian cancer." (PMID 33718147, 2021). "Further investigation into the potential role of c-MYC as a prognostic marker in ovarian cancer is required in the context of histological subtypes, disease subgroups, genetic racial/ethnic differences, and reliable detection methods." (PMID 33718147, 2021). "Mechanistically, MBZ was shown to inhibit multiple cancer-associated signaling pathways including ELK/SRF, NFKB, MYC/MAX, and E2F/DP1 in cisplatin-resistant ovarian cancer cells." (PMID 34232919, 2021). "Taken together, these data suggested that USP39 is a direct transcriptional target of c-MYC in ovarian cancer cells." (PMID 33731694, 2021). "In conclusion, we have identified an MYC-driven polyamine signature that reflects the early pathogenesis of ovarian cancer." (PMID 33671595, 2021). "In primary tumors of HGSOC, co-upregulation of FAK and c-MYC suggest a co-targeting approach as a therapeutic strategy in ovarian cancer." (PMID 33718147, 2021). "Here, we briefly describe the frequency of c-MYC deregulation in ovarian cancer and the consequences of its targeting." (PMID 33718147, 2021). "Overall, the clinical significance of c-MYC mRNA expression in ovarian cancer has been inconsistent." (PMID 33718147, 2021). "Assessment of the clinical relevance of phosphorylated c-MYC in ovarian cancer warrants further investigation." (PMID 33718147, 2021). "Similar reports showed that c-MYC mRNA levels were higher in early-stage ovarian cancer tissues compared with those in normal samples, as evident by qPCR analysis." (PMID 33718147, 2021). "Early reports showed that targeting c-MYC in vitro with triplex-forming (TFOs) and liposomal phosphorothioate oligonucleotides (PTOs) inhibits ovarian cancer cell growth." (PMID 33718147, 2021). "For example, miR-654-5p was identified to be a suppressor for ovarian cancer by targeting to different genes that included in MYC, WNT and AKT pathways." (PMID 32640974, 2020). "We further measured HMGA1P6 and HMGA1/2 expression in ovarian cancer cell lines with MYC overexpression or knockdown." (PMID 32127525, 2020). "The results show that NGF increased the transcriptional activity of MYC in ovarian cancer cell lines (p < 0.05)." (PMID 33081077, 2020). "miR-145 was described as a suppressor miRNA that directly targets the MYC transcript in esophageal squamous cell carcinoma and ovarian cancer." (PMID 32283808, 2020). "It has been reported that SRC is activated by EPHB4 in ovarian carcinoma models suggesting the role of SRC kinase in regulation of MYC." (PMID 31641103, 2019). "c-MYC is often amplified in ovarian cancers and has previously been proposed as a therapeutic target in platinum-resistant cases." (PMID 31775874, 2019). "Further study is required to determine if EHMT1/2 interacts with MYC, or other pro-survival signaling pathways, in the context of PARPi-resistant ovarian cancer." (PMID 31775874, 2019). "Bromodomain inhibitors such as JQ1 have been shown to down-regulate MYC expression in MYC-amplified tumors, which sensitizes ovarian cancer cells to platinum-based therapy." (PMID 31727874, 2019).
ovarian carcinoma (continued). "MYC had the highest frequency of copy number variations (6/21, 29%) in recurrent ovarian cancer patients, followed by RB1 (6/21, 29%) and PIK3CA (3/21, 14%)." (PMID 29797793, 2018). "For this reason, we tested if MYC overexpression in ovarian cancer induces Pol I-mediated rRNA transcription as well as Pol II-mediated transcription of “Pol I regulon” genes." (PMID 29435159, 2018). "According to The Cancer Genome Atlas, MYC amplification/upregulation is frequent in cancer, including ovarian cancer, where it is detected in over 30% of cases." (PMID 29435159, 2018). "In conclusion, hub genes (such as TGFA, EGFR, ErbB2, and MYC) and key pathways (such as the ErbB signaling pathway) closely related to the proliferation of ovarian cancer cells in hypoxia were identified by bioinformatics analysis." (PMID 29482638, 2018). "We demonstrate that ovarian cancer cells highly depend on MYC for maintaining their oncogenic growth, indicating MYC as a therapeutic target for this difficult-to-treat malignancy." (PMID 30422115, 2018). "In conclusion, combining CX-5461 with drugs inhibiting either mt-rRNA transcription (e.g. 2’C-MeA) or mitoribosome function (e.g. doxycycline) seems to be an effective antiproliferative strategy to treat MYC-overexpressing ovarian cancer." (PMID 29435159, 2018). "In drug‐sensitive recurrent ovarian cancer patients, MYC had the highest frequency of copy number variations (3/11, 27%), followed by RB1 (2/11, 18%), and PTK2 (2/21, 10%)." (PMID 29797793, 2018). "Small interfering RNA–mediated reduction in either PVT1 or MYC expression can inhibit cellular proliferation of ovarian cancer." (PMID 28430593, 2017). "In patients with ovarian cancer, high levels of MYC are coupled to tumor recurrence, poor overall survival, and cisplatin resistance." (PMID 28590415, 2017). "An obvious feature of ovarian cancer is the presence of recurrent regions of copy number gains or losses, and rare recurrent genomic events contain known oncogenes, such as MYC and CCNE1 in our analysis." (PMID 26735889, 2016). "By contrast, N-MYC and L-MYC expression levels correlated with c-MYC expression signatures only in medulloblastoma and ovarian carcinoma, respectively, and in these tumours the signatures correlated negatively with BPTF expression levels." (PMID 26729287, 2016). "Loss-of-function studies further demonstrated that C17orf91 repression impaired migration, invasion and viability of ovarian cancer cells, and downregulated the pro-metastatic gene, MYC, at both mRNA and protein level." (PMID 27535740, 2016). "We therefore explored MYC and SQLE associations in terms of GE and CN in the breast and ovarian cancer TCGA datasets." (PMID 26777065, 2016). "We used NDRG1, a downstream tumor suppressor gene of the MYC signaling pathway in ovarian cancer, as an example." (PMID 27029057, 2016). "We herein demonstrated that c-MYC and KRAS accelerated the production of ovarian cancer-associated ascites." (PMID 27483433, 2016). "Further supporting a role for c-Myc in metformin resistance, ovarian cancer cell lines with MYC gene amplification were relatively insensitive to metformin treatment even in normoglycemic conditions." (PMID 26172303, 2015). "The consistent induction of FZD5 and MYC is especially interesting, considering that both are frequently expressed at high levels in ovarian cancer cells compared to immortalized ovarian surface epithelial cells (IOSE398)." (PMID 26121572, 2015). "Dysregulation of the JAG1-Notch1 signaling cascade has been shown to activate a wide range of oncogenes in the HES, HEY and MYC families, thereby leading to ovarian cancer progression and chemoresistance." (PMID 24659709, 2014). "Analyses of TCGA data suggest similar relationships between ATAD2, 8q24 amplification, and MYC pathway activation in glioblastoma, breast, and ovarian cancers." (PMID 23393560, 2013).
ovarian carcinoma (continued). "In ovarian cancer, a few of the interesting interacting genes include MYC, a well-known oncogene and TRIB1, a novel regulator of the MAP kinase pathway recently linked to leukemogenesis." (PMID 23822816, 2013). "In the GBM data, the involved pathways include parts of the RB signaling and RTK signaling pathways (CDKN2B, CDK4; EGFR, NF1 ), and in the ovarian carcinoma data a recurrent mutated module related to cell cycle and DNA repair (CCNE1, MYC, RAD52 ) is revealed." (PMID 24565034, 2013). "To test this possibility we compared expression of MYC in amplified ovarian cancer samples to expression in normal fallopian tube epithelium." (PMID 20386695, 2010). "On the other hand, IPA analysis showed several genes interacting with SRC or MYC, each of which was reported as a representative gene in oncogenic pathways of ovarian cancer." (PMID 20300634, 2010). "In ovarian cancer, associations have been found between CCNE1 and 12p amplification, and between MYC and 20q amplification by fluorescence in situ hybridisation." (PMID 20844748, 2010). "MYC is a multifunctional proto-oncogene and activated in about 30% of ovarian cancer by several mechanisms." (PMID 20300634, 2010). "PLK1 protein levels in ovarian cancer cells also seem to correlate with MYC and HSF1 levels." (PMID 39831777, 2025). "In light of the penetrant anti-clonogenic effect of the SAEi on MYC-High cells, we asked whether ovarian cancer cell lines displayed differential sensitivity to the SAEi." (PMID 40487451, 2025). "KRAS has been shown to be amplified in ovarian endometrioid carcinoma and HGSOC and has been associated with an aggressive phenotype of metastatic uterine endometrioid carcinoma, whereas MYC amplifications have been observed in a variety of ovarian cancers, including endometrioid carcinomas." (PMID 40981433, 2025). "MYC is an oncogene frequently amplified in ovarian cancer and required for cancer cell growth." (PMID 38256218, 2024). "MYC is located on chromosome 8q24, a commonly amplified region in ovarian carcinomas." (PMID 36765581, 2023). "Furthermore, focal amplification of a 23 kb lung adenocarcinoma-specific super-enhancer ~450 kb downstream of the MYC promoter and a 10 kb ovarian-cancer-specific super-enhancer ~800 kb downstream of the MYC promoter was also detected." (PMID 37443779, 2023). "The analysis of the expression levels of the BCL2 and c-MYC genes showed a decrease in the transcript level in patients with ovarian cancer compared to the control group (BCL2: 17.46% ± 3.26 vs. 100% ± 8.32; p < 0.05, c-MYC: 37.56% ± 8.16 vs. 100% ± 9.12; p < 0.05)." (PMID 38003498, 2023). "c-MYC plays a key role in promoting ovarian cancer initiation and progression." (PMID 36765581, 2023). "In this review, we discuss the significance of c-MYC and its paralogues in ovarian cancer." (PMID 36765581, 2023). "Moreover, c-MYC amplified chemotherapy-resistant ovarian cancer cells were demonstrated to be highly sensitive to combinational JQ1 and GS-626510, a bromodomain and extra-terminal motif inhibitor." (PMID 36765581, 2023). "Also, these liposomes efficiently delivered c-MYC-targeted siRNA in a xenograft mouse model of ovarian cancer and miR-143-OMIs in a subcutaneous GBM mouse model." (PMID 37752997, 2023). "The MYC gene is frequently amplified in ovarian cancer (> 30% of patients)." (PMID 37202753, 2023). "High MYC expression is an independent factor of tumor proliferation in ovarian cancer." (PMID 35370699, 2022). "Celastrol could interact with c-MYC to inhibit cell proliferation and induce apoptosis in ovarian cancer." (PMID 35370699, 2022). "We considered that celastrol might directly interact with MYC to regulate cell proliferation, DNA repair and replication, and apoptosis in ovarian cancer cells." (PMID 35370699, 2022).
ovarian carcinoma (continued). "Furthermore, we found that MYC was positively correlated with WEE1 in GEPIA ovarian cancer database." (PMID 35173547, 2022). "Furthermore, ovarian cancer cell lines and primary cultures showed the same topotecan-elicited MYC expression profiles." (PMID 35844787, 2022). "Interestingly, MYC was positively correlated with HJURP both in GEPIA ovarian cancer database and in 30 tumor specimens from our laboratory." (PMID 35173547, 2022). "MiR-145 suppressed glutamine metabolism in ovarian cancer cells via the c-MYC/GLS1 pathways, which might enhance the existing cancer detection and treatment method." (PMID 36483029, 2022). "c-MYC was correlated with poor survival of ovarian cancer patients." (PMID 35370699, 2022). "Additionally, we investigated that silencing HJURP increased sensitivity of ovarian cancer cells to cisplatin via MYC/WEE1 axis, and HJURP participated in DNA repair of cisplatin-induced damage." (PMID 35173547, 2022). "In addition, c-MYC had a higher frequency of copy-number variations in recurrent patients with ovarian cancer." (PMID 35370699, 2022). "Recently, several studies indicated that a combination of Olaparib with CDK4/6i displayed therapeutic synergy in MYC highly expressed breast and ovarian cancers with HR proficiency, which represents a new treatment paradigm in these cancers beyond HR-deficiency." (PMID 35270034, 2022). "Similar to amplification and mRNA expression, the association between c-MYC protein levels and clinical parameters in ovarian cancer is not clear." (PMID 33718147, 2021). "In addition, siRNA-mediated silencing of the histone deacetylase HDAC1 suppresses cell proliferation, increases apoptosis, and sensitizes ovarian cancer cells to cisplatin treatment by inducing c-MYC downregulation and miR-34a upregulation." (PMID 33718147, 2021). "Moreover, targeting c-MYC with siRNAs in platinum-resistant ovarian cancer significantly inhibits cell growth and viability, induces cell-cycle arrest and activates apoptosis in vitro, and reduces tumor growth in vivo." (PMID 33718147, 2021). "Taken together, these observations suggest that although c-MYC gene copy-number variation and amplification have been commonly reported in ovarian cancer, a relationship between c-MYC gene aberrations and prognostic or clinicopathological significance has not been clearly established." (PMID 33718147, 2021). "Finally, in ovarian cancer, MYC amplification predicted synergistic benefit from a combination of PARP inhibition with olaparib and CDK-4 inhibition with palbociclib." (PMID 34638300, 2021). "Moreover, c-MYC inhibition with 10058-F4 reduces glutamine uptake in cisplatin-resistant ovarian cancer cells." (PMID 33718147, 2021). "Importantly, USP39 was transcriptionally activated by the oncogene protein c-MYC in ovarian cancer cells." (PMID 33731694, 2021). "In addition, PVT1 was shown to act independently of MYC, when amplified and overexpressed, through increasing cell proliferation and inhibiting apoptosis in breast and ovarian cancer cell lines." (PMID 33670447, 2021). "MYC is an oncogenic driver in the pathogenesis of ovarian cancer." (PMID 33671595, 2021). "Reports on the prognostic value of c-MYC in ovarian cancer have been inconsistent, which may be explained in part by the complexity of the disease, patient background, and choice of methodology." (PMID 33718147, 2021).
ovarian carcinoma (continued). "We then measured USP39 expression in ovarian cancer cells with c-MYC overexpression or knockdown." (PMID 33731694, 2021). "Moreover, biomarkers of sensitivity to CX-5461 in ovarian cancer models include BRCA-mutated and MYC targets gene expression signatures and were found to be enriched in a subset of primary and relapsed ovarian cancer." (PMID 34440328, 2021). "Thus, c-MYC targeted therapy is a potential treatment for ovarian cancer patients with high expression of c-MYC, including those who are resistant to cisplatin." (PMID 32660514, 2020). "In fact, the amplification of c-MYC has been reported in ovarian cancer." (PMID 32660514, 2020). "Previous studies showed that higher levels of c-MYC expression led to a faster recurrence and worse overall survival rate of patients with high grade serous ovarian cancer and was related to cisplatin resistance of ovarian cancer cells." (PMID 32660514, 2020). "Silencing of c-MYC inhibited the growth of cisplatin-resistant ovarian cancer." (PMID 32660514, 2020). "However, c-MYC is also increased in cisplatin-resistant ovarian cancer cells, which would result in the upregulation of the miR-17-92 cluster, including miR-18a." (PMID 33392094, 2020). "The miR-145 and miR-23b are two oncosuppressor miRs that are known to be downregulated in ovarian cancer tissues and in-silico analysis revealed that c-MYC and VEGF could be targets for these miRs, which in turn are modulated by NGF/TRKA." (PMID 33081077, 2020). "Our findings reveal that MYC may contribute to oncogenesis through transcriptional regulation of pseudogene HMGA1P6 in ovarian cancer." (PMID 32127525, 2020). "In this study we found that CAOV4 ovarian cancer cells overexpressing endogenous MYC show upregulation of nucleolar rRNA and “Pol I regulon” genes as well as increased mitochondrial rRNA transcription and upregulation of MYC-target genes involved in mitochondrial rRNA transcription and ribogenesis." (PMID 29435159, 2018). "The expression of MYC was increased by hypoxia in ovarian cancer cells, which may contributed to the observed resistance to platinum compounds." (PMID 29482638, 2018). "Our data suggest that combined inhibition of transcriptional CDKs with THZ1, or its derivatives, may be an effective approach for treating MYC-dependent ovarian cancer." (PMID 30422115, 2018). "However, additional studies are required to prove the interaction of rs6983267 with c-MYC and other transcription factors in the pathogenesis of ovarian cancer." (PMID 28430593, 2017). "In the present study, which focused on angiogenesis and inflammation, we established oncogene-transduced mouse ovarian cancer cell lines by transducing c-MYC and KRAS into the mouse ovarian epithelial immortalized cell line, ID8, which has been established from C57BL/6 mice." (PMID 27483433, 2016). "Actually, hyperglycemia seems to favour MYC-dependent enhanced aerobic glycolysis and tumor cell survival in the presence of metformin (a suppressor of MYC expression), at least in a murine model of ovarian cancer." (PMID 27164115, 2016). "VEGF concentrations in ascites significantly increased in c-MYC-induced ovarian cancer, whereas the concentrations of inflammatory cytokines in ascites were significantly high in KRAS-induced ovarian cancer and were accompanied by an increased number of neutrophils in ascites." (PMID 27483433, 2016). "Amplification of MYC occurs in many cancers, including more than 40% of ovarian cancers." (PMID 26018524, 2015). "In addition, 8q11.1q24 region, which is amplified in the three samples analysed by CGH, includes among other genes MYC, a key inductor of proliferation which has been shown to be commonly amplified in ovarian cancer." (PMID 26620706, 2015). "These novel findings suggest that the growth of ovarian cancer cells is dependent upon c-MYC activity and that targeting c-Myc-Max heterodimerization could be a potential therapeutic strategy for ovarian cancer." (PMID 25143136, 2014).